TPP2 (tripeptidyl peptidase 2)
Description:
Cytosolic tripeptidyl-peptidase that releases N-terminal tripeptides from polypeptides and is a component of the proteolytic cascade acting downstream of the 26S proteasome in the ubiquitin-proteasome pathway. It plays an important role in intracellular amino acid homeostasis. Stimulates adipogenesis (By similarity).
Synonyms: TPP-2; TPP-II; TPPII; IMD78
Tractability: PROTAC: ubiquitination databases record sites on it; its protein half-life has been measured; a small molecule that binds it is known.
Target class: Enzyme; Serine protease SB clan; Protease; Serine protease; Serine protease S8A subfamily
Gene: Protein-coding gene on chromosome 13 (102,596,958 to 102,679,958, forward strand). Ensembl gene ENSG00000134900.
Subcellular location: Cytoplasm; Nucleus
Subcellular location (Human Protein Atlas): Cytosol; Nuclear bodies
Pathways (Reactome):
Immune System: Antigen processing: Ubiquitination & Proteasome degradation
Gene Ontology:
Molecular function: aminopeptidase activity; identical protein binding; protein binding; tripeptidyl-peptidase activity; endopeptidase activity; exopeptidase activity; serine-type endopeptidase activity; serine-type peptidase activity
Biological process: intracellular amino acid homeostasis; protein polyubiquitination; proteolysis
Cellular component: cytosol; nuclear body; cytoplasm; nucleus
Genetic constraint (gnomAD): Loss-of-function variants: 27 observed, 128.2 expected, observed/expected ratio (o/e) 0.21, 90% interval 0.15 to 0.29. The upper end of that interval is the gene's LOEUF score, 0.29, which puts it in group 1 of 6, group 1 being the genes least tolerant of losing a copy. Missense variants: 934 observed, 1,404.3 expected, observed/expected ratio (o/e) 0.67, 90% interval 0.63 to 0.7. Synonymous variants: 468 observed, 494.24 expected, observed/expected ratio (o/e) 0.95, 90% interval 0.88 to 1.02.
Gene-disease validity (ClinGen):
ClinGen rates the evidence that TPP2 causes each of these diseases.
immunodeficiency 78 with autoimmunity and developmental delay (autosomal recessive): Definitive.
Homologues: Orthologues: chimpanzee TPP2 (99% identical), macaque TPP2 (99% identical), guinea pig TPP2 (98% identical), rabbit TPP2 (97% identical), rat Tpp2 (97% identical), dog TPP2 (97% identical), mouse Tpp2 (96% identical), pig TPP2 (92% identical), tropical clawed frog tpp2 (82% identical), zebrafish tpp2 (75% identical), Drosophila melanogaster TppII (38% identical), Caenorhabditis elegans tpp-2 (35% identical). Paralogues in human: PCSK5 (13% identical), PCSK9 (11% identical), PCSK6 (11% identical), PCSK1 (10% identical), MBTPS1 (9% identical), FURIN (9% identical), PCSK4 (9% identical), PCSK7 (8% identical), PCSK2 (7% identical).
Diseases named in the same sentence as TPP2 in open-access papers:
TPP2 is named in the same sentence as 39 diseases in open-access papers, as found by Europe PMC text mining. Sharing a sentence is not in itself a finding about the gene and the disease. The quoted sentences say what the papers report.
Autoimmunity (3 papers, 2017 to 2023). The occurrence of an immune reaction against the organism's own cells or tissues. "Likewise, the human TPP2 deficiency is a PID linking premature immunosenescence to severe autoimmunity." (PMID 31799221, 2019). "One recent example is the discovery of autosomal recessive mutations in the tripeptidyl peptidase-2 (TPP2) gene, which causes a combined immunodeficiency, autoimmunity, and neurodevelopmental delay." (PMID 28408979, 2017).
Immunodeficiency (3 papers, 2017 to 2024). Failure of the immune system to protect the body adequately from infection, due to the absence or insufficiency of some component process or substance. "It has been reported that a mutation in tripeptidyl peptidase II (TPP2) or in phosphoinositide 3-kinase (PI3K), leads to TPP2 deficiency or activated PI3K, finally results in premature senescence of T cells and immunodeficiencies." (PMID 39376566, 2024).
atopic dermatitis (1 paper, 2024). "It was reported that humans with homozygous TPP2 deficiency are predisposed to develop autoimmune disorders, including atopic dermatitis." (PMID 39273140, 2024). "The main objective of our work was to differentiate between healthy skin (C), atopic dermatitis (AD) and psoriasis vulgaris (PV) biopsies on the base of involucrin (IVL) and human β-defensin-2 (hBD-2) concentrations and their mRNA, as well as mRNA for TPP2 and PSMB8." (PMID 39273140, 2024).
breast carcinoma (1 paper, 2022). "To determine whether XBP-1s directly binds to the TPP2 gene, we reviewed the ENCODE chromatin immunoprecipitation-sequencing (ChIP-seq) database and found that the TPP2 promoter displayed XBP-1 ChIP peaks in the breast cancer cell lines HS578T, MDA-MB-231, and T47D." (PMID 35794100, 2022).
chronic mucocutaneous candidiasis (1 paper, 2021). "Susceptibility to predominantly viral infections was observed in TET2, TPP2 and TNFAIP3 patients while chronic mucocutaneous candidiasis (CMC) and mendelian susceptibility to mycobacterial disease (MSMD) were characteristic of STAT1 GOF and IL12RB1 patients, respectively." (PMID 34447369, 2021).
Cognitive impairment (1 paper, 2024). Abnormal cognition is characterized by deficits in thinking, reasoning, or remembering. "Recently, a family was described with deletion of TPP2 gene, where either cognitive impairment or immune system imbalance was dominant, with a tendency for the development of inflammatory skin diseases, including AD." (PMID 39273140, 2024).
dementia (1 paper, 2024). Loss of intellectual abilities interfering with an individual's social and occupational functions. "Consistent with the critical importance of PC and Ca2+ in the CNS, we further found TPP2 depletion causes presenile dementia in female mice, which is closely associated with Ca2+ dyshomeostasis, PC deficit, and abnormal autophagic degradation of aromatase." (PMID 38389851, 2024). "This study therefore discloses a new function of TPP2 which not only makes great sense for elucidating the pathogenesis and future treatment of dementia, but also for interpreting the role of TPP2 in other system and treatment of the related disorders." (PMID 38389851, 2024). "These abnormalities cause ATF6-SYVN1-UCHL1 axis-mediated autophagic aromatase degradation and estrogen deficit, culminating in presenile dementia of both ubiquitous and excitatory neuron-specific TPP2 knockout female mice." (PMID 38389851, 2024). "Thus, this study is not only of great significance for elucidating the pathogenesis of dementia and its futural treatment, but also for interpreting the role of TPP2 in other systems and their related disorders." (PMID 38389851, 2024).
infertile (1 paper, 2020). "Sperm maturation proteins such as CLU and TPP2 were also reported to be overexpressed in idiopathic infertile men following treatment with antioxidant formulation." (PMID 32155908, 2020).
inflammatory skin disease (1 paper, 2024). Inflammatory skin disorders covers a broad category that includes many conditions ranging in severity, from mild itching to grave medical health complications These disorders are common in people of all ages and races. "No other correlation was found among IVL, hBD-2, IVL mRNA, hBD-2 mRNA, TPP2 mRNA and PSMB8 mRNA, neither in the patients with inflammatory skin diseases nor in the control group." (PMID 39273140, 2024). "Tripeptidyl peptidase 2 is involved in the regulation of HIV responses, but the role of TPP2 in inflammatory skin diseases has not yet been understood." (PMID 39273140, 2024).
Intellectual disability (1 paper, 2024). "Whereas, TPP2 deficiency is linked to immunosenescence, lifespan regulation, human intellectual disability, and sterile brain inflammation mimicking multiple sclerosis (MS) 5-7." (PMID 38389851, 2024).
lung carcinoma (1 paper, 2023). "We further investigated whether miR-660-5p promoted proliferation and metastasis of lung cancer cells via LIMCH1, SMARCA5, and TPP2." (PMID 38057344, 2023).
melanoma (1 paper, 2022). A malignant, usually aggressive tumor composed of atypical, neoplastic melanocytes. "siRNA-mediated TPP2 knockdown significantly upregulated MHC-I expression on TSCC and B16F10 melanoma cells, showing that TPP2 inhibits MHC-I expression." (PMID 35794100, 2022).
multiple sclerosis (1 paper, 2019). A progressive autoimmune disorder affecting the central nervous system resulting in demyelination. "A recent study of a large cohort of patients with multiple sclerosis (MS) could identify TPP2 mutations as causative in three affected siblings of a consanguineous Syrian family." (PMID 31799221, 2019).
Neurodevelopmental delay (1 paper, 2019). "Of note, some TPP2 patients showed neurodevelopmental delay." (PMID 31799221, 2019).
Obesity (1 paper, 2020). Accumulation of substantial excess body fat. "Another point to be discussed is that the present study is the first to identify an association between TPP2, PSMC6, ARL6IP1 and FAM49B genes with obesity." (PMID 32296077, 2020).
cancer (3 papers, 2010 to 2023). A tumor composed of atypical neoplastic, often pleomorphic cells that invade other tissues. "Since TPP2 regulates cancer cell immunogenicity by degrading antigenic peptides, it can be inferred and experimentally verified that mitochondrial fission inhibition would not affect the expression of other immunological-related or unrelated transmembrane proteins." (PMID 35794100, 2022). "Following Tpp2 knockdown, mouse IFN-γ concentration and specific lysis of cancer cells significantly increased at every E/T ratio tested." (PMID 35794100, 2022).
tumor (3 papers, 2010 to 2022). "Similar to Tpp2, Topors was also identified as having a pro-longevity effect and also found to act as a tumor suppressor." (PMID 27115072, 2016). "XBP-1s is a transcription factor for aminopeptidase TPP2, which inhibits MHC-I complex cell surface expression likely by degrading tumor antigen peptides." (PMID 35794100, 2022).
infection (1 paper, 2022). The state of being infected such as from the introduction of a foreign agent such as serum, vaccine, antigenic substance or organism. "Interestingly, the level of genes encoding peptidases (Tpp1, Tpp2, Nrd1, Erap1), which are known to be required for the generation of most MHC class I-binding peptides, were decreased after infection." (PMID 36318581, 2022).
neurological diseases (1 paper, 2024). "Rationale: Tripeptidyl peptidase II (TPP2) has been proven to be related to human immune and neurological diseases." (PMID 38389851, 2024).
TPP2 also shares sentences with these, for which no sentence is quoted: Burkitt lymphoma (3 papers); autoimmune lymphoproliferative syndrome (2); lymphoma (2); anemia (1); Anxiety (1); autoimmunity disorders (1); Cachexia (1); chronic granulomatous disease (1); depression (1); Evans syndrome (1); genetic disorders (1); inflammatory bowel disease (1); iron deficiency (1); myocardial infarction (1); prolidase deficiency (1); psoriasis (1); psoriasis vulgaris (1); squamous cell carcinoma (1); Thrombus (1); viral infections (1).